MSR1 (macrophage scavenger receptor 1)
Diseases named in the same sentence as MSR1 in open-access papers (continued):
Sharing a sentence is not in itself a finding about the gene and the disease.
tumor (continued). "Three tumor-associated macrophage (TAM) markers, MSR1/CD204, CD86, and CD68, exhibited a 6-fold (p < 0.0001), 8.9-fold (p < 0.0001), and 15.6-fold increase in mRNA expression levels, respectively, in LGG tumors." (PMID 38539537, 2024). "Positive correlations with TIM3 and PD-L1 were identified in the tumor types studied, signifying that MSR1 is abundant in an immune-suppressive environment." (PMID 38612803, 2024). "Clusters 1, 5, 11, and 17 all appeared to express significant amounts of CD163 (except cluster 11) and MSR1 (encodes CD204) and variable MRC1 (encodes CD206), classic markers of immunosuppressive/tissue reparative/tumor promoting M2 macrophages." (PMID 36966348, 2023). "Consistent with our observations, we noted a clear increase in the prevalence of SIRPA+MSR1+-expressing macrophage subpopulations in tumour tissues (77.3% of all macrophages) compared with normal tissues (24.6% of all macrophages)." (PMID 36442992, 2023). "Previous studies demonstrated that MSR1 exhibited high expressions in M2-like pre-tumor macrophages, which were related to tumorigenesis and development, including immunosuppressive factor generation and angiogenesis." (PMID 37370848, 2023). "In line with our previous results, the drug-mediated SPHK1 inhibition resulted in a strong reduction of Arg1 and Msr1 expression in the tumor-microglia co-culture." (PMID 36672428, 2023). "Whilst these investigations provide valuable insight into the link between these TAMs and aggressiveness of the tumour, they offer limited functional or mechanistic insight into the pathophysiologic activity of MSR1 in the TME." (PMID 36325338, 2022). "A significant link between the number of MSR1+ macrophages and lymphangiogenesis was also observed in pancreatic ductal adenocarcinoma thus providing insight into how these tumour-promoting macrophages facilitate metastasis." (PMID 36325338, 2022). "It has recently been published that not only is the MSR1 marker relevant in tumour prognosis but also the ratio of T cells, B cells, and MSR1+ TAMs." (PMID 36325338, 2022). "Coupled with low toxicity to normal tissue, these results show promise in targeting TAMs via MSR1 to reduce their effect on tumour growth and metastasis." (PMID 36325338, 2022). "To further confirm the field effects of p‐STAT3, Mcm2 + luminal to basal ratio, and MSR1 + cell number, we detected the immunoreactivity of the p‐STAT3 and MSR1 + cell number in the PCa, pericancer tissues near and far from tumor core, and benign tissues." (PMID 32860339, 2020). "Similar to other critical tumor suppressors like Pten and Msr1, it was observed that Egr1 expression is down-regulated by BCR-ABL both in vitro as well as in vivo." (PMID 29050203, 2017). "We found variants in the five genes APC, BRCA1, RET, RNASEL, and STK11 that were linked to autosomal dominant forms of cancer or neoplasm as well as four complex risk variants in ELAC2, MSR1, AIP, and SDHB." (PMID 25333069, 2014). "The therapeutic relevance of MSR1 and lipid uptake is reinforced by studies showing that direct targeting of MSR1 promotes tumor immunity." (PMID 24523723, 2014). "We next evaluated the level of expression of the macrophage scavenger receptor (Msr1), which has been shown to be up regulated in tumor resident DCs and responsible for the increased lipid uptake by DCs in tumor bearing hosts." (PMID 22911764, 2012). "For these experiments DCs were isolated from established tumors and incubated with Mam-A2.4 splenocytes, Mam-A2.4 specific peptide and tumor-explant supernatants along with 0, 10, 25 or 50 μg/ml of anti-Msr1." (PMID 22911764, 2012). "Secondly, this single low dose of TBI impacts the biology of tumor derived DCs by reducing both Msr1 expression and lipid uptake both of which have been shown to affect the ability of DCs to present tumor antigen." (PMID 22911764, 2012).
tumor (continued). "To determine if blocking Msr1 directly affects lipid uptake we incubated tumor-derived DCs with tumor explants supernatants and anti-Msr1 for 4 hrs." (PMID 22911764, 2012). "In particular, our analysis revealed increased expression of various immune modulatory molecules (CD274 (PD-L1), OSM, PTGES2, CD36, and MSR1) by tumor-infiltrating monocytes and neutrophils suggesting an immune suppressive role is adopted following infiltration into the TME." (PMID 39932553, 2025). "The downregulation of HY scRNA pseudogene transcription in conjunction with MSR1 RNA up-regulation might be a feature of tumor tissues." (PMID 39194722, 2024). "These pathways have been implicated in angiogenesis, the induction of M2-like polarization in macrophages, and tumor metastasis, suggesting that MSR1 may promote angiogenesis and metastasis in TNBC, contributing to poor prognosis." (PMID 39776914, 2024). "This suggests that MSR1 may play a role in macrophage-induced tumor activation and act as a molecular switch regulating gene expression." (PMID 39502334, 2024). "Shp2f/fLysMCre MDSCs also exhibited lower expression of Msr1, which promotes neutrophil netosis, a protumorigenic process, and Xbp1, a classical marker of the unfolded protein response, which polarizes tumor-infiltrating myeloid cells to highly immunosuppressive MDSC20." (PMID 36581713, 2023). "Further studies revealed that MSR1 might be involved in changes in the tumor microenvironment (TME) and was a potential prognostic biomarker in LGG." (PMID 37370848, 2023). "Additionally, some DGC patients tested negative for CDH1/CTNNA1 gene but had pathogenic variants in related tumor susceptibility genes, such as BRCA2, ATM, SDHB, PRSS1, MSR1, STK11, and PALB2." (PMID 37393258, 2023). "The results of GO and KEGG enrichment analysis suggest that MSR1 may play a role in tumor immune‐related functions and pathways." (PMID 35142109, 2022). "Furthermore, there is mounting evidence that MSR1 itself holds some pro-tumour activity with targetable signalling pathways remaining elusive." (PMID 36325338, 2022). "Proteomic analyses have attempted to discover the tumour cell ligands that could activate MSR1 in TAMs." (PMID 36325338, 2022). "A growing number of studies suggest that MSR1 may play a role in macrophage‐induced tumor activation and act as a molecular switch to regulate gene expression." (PMID 35142109, 2022). "Further suggesting a role for MSR1 in benign to malignant transformation of tumours." (PMID 36325338, 2022). "This link may be important for the activity of MSR1 in the tumour microenvironment, as will be discussed later in this review." (PMID 36325338, 2022). "Blocking MSR1 impaired FA accumulation in DCs, which could stimulate the expansion and cytotoxicity of adoptively transferred tumor-specific CD8+ T cells in breast tumors." (PMID 34742349, 2021). "Using either 5-(tetradecycloxy)-2-furoic acid (TOFA), an inhibitor of acetyl-CoA carboxylase (ACC) that participates in fatty acid synthesis, or neutralizing antibodies to MSR1 before the incubation of DCs with tumor supernatant, substantially enhanced the anti-tumor potency of DCs vaccination." (PMID 32823961, 2020). "There is evidence that a substantial proportion of DCs in both tumor models and cancer patients have increased amounts of lipids, specifically triglycerides, due to increased synthesis of fatty acids or increased lipid uptake from plasma via MSR1." (PMID 32823961, 2020). "This suggests that JNK signalling downstream of polyubiquitylated MSR1 is present in TAMs of human cancers and could potentially be involved in tumour promotion." (PMID 31028084, 2019). "The aberrant lipid accumulation in DCs is fostered by yet-unknown factors secreted by tumor cells and mediated by macrophage scavenger receptor 1 (Msr1) on DCs, a receptor that binds primarily modified lipoproteins." (PMID 31073300, 2019).
tumor (continued). "Our data suggest that MSR1 labels a subset of anti-tumour TAMs in Pca, which may inhibit tumour progression." (PMID 29137340, 2017). "However, the tumor-derived factors that up-regulate MSR1 are poorly characterized, and it is yet to be definitively shown that lipid is an immunoregulatory ligand for MSR1on DC." (PMID 24523723, 2014). "Thus we propose an additional mechanism of action of TBI is through the down regulation of Msr1 which results in the inhibition of lipid uptake by tumor resident DCs thus enabling them to present tumor antigen more efficiently." (PMID 22911764, 2012). "Our data show that TBI induced the down-regulation of Msr1 and prevents tumor resident DCs from lipid uptake thereby potentially increasing the functional capacity of the adoptively transferred Mam-A specific CD8 T cells to induce tumor regression and prevent relapse." (PMID 22911764, 2012). "Furthermore, we show that blocking Msr1 on tumor derived DCs in vitro induces the proliferation and expansion of Mam-A specific CD8 T cells in greater numbers than cultures that received irradiated tumor derived DCs." (PMID 22911764, 2012). "In contrast, in mouse tumor models and patients with cancer, the capability of cDCs to process tumor antigens and activate T cells effectively will be weakened by the accumulation of lipids, which is caused by FAS activation and lipid uptake through the increased expression of Msr1." (PMID 33413697, 2021). "The observation that the treatment produced an increase in the expression levels of ARG1 and MSR1 in NR, while a decrease in R patients supported the hypothesis that an alternative polarisation of macrophages occurred, improves tumour tolerance and generates anti-PD1 resistance." (PMID 32317723, 2020). "This process is observed in TAMs within ovarian cancer tissue, where elevated MSR1 ubiquitylation and JNK activation contribute to the inflammatory environment, potentially promoting tumor progression and metastasis." (PMID 40330466, 2025). "Overall, these findings indicate that MSR1 is significantly upregulated in THCA tissues and is involved in critical pathways related to tumor progression and immune response." (PMID 39502334, 2024). "The expression of two TAM markers in our studies revealed that macrophage scavenger receptor 1 (MSR1/CD204) and CD86 were expressed at very low levels in normal tissue (less than 0 log2 TPM; <1 TPM) and exhibited increased levels in tumor tissue." (PMID 38539537, 2024). "The most important markers of TAMs have been identified by studying tumours at different sites: CD163, CD204 (MSR1), CD206 (MRC1), MARCO, SIGLEC1 (CD169), stabilising protein-1 (Stab1) and Tie2 (TEK)." (PMID 39060648, 2024). "These analyses highlight the critical role of MSR1 in modulating immune cell infiltration in THCA, emphasizing its potential as a therapeutic target for enhancing anti-tumor immunity." (PMID 39502334, 2024). "On the other hand, the expression of many M2 signature genes—including those for FN1, MARCO, MRC1, MSR1, TGF-β1, and TGM2—decreased with tumor progression." (PMID 37441079, 2023). "Difference analysis and correlation analysis were used to study the relationship between MSR1 and TME‐related scores, tumor‐infiltrating immune cells (TIICs), immune‐related gene sets, and immune checkpoints (ICPs)." (PMID 35142109, 2022). "It is clear that MSR1 acts within the TME, however a defined tumour-specific ligand and signalling cascade are yet to be clarified, this therefore requires further investigation." (PMID 36325338, 2022). "Only a few macrophage genes such as PPARG, MSR1/CD204, and MARCO were downregulated in TAMs compared to non-tumor macrophages in our dataset." (PMID 33918618, 2021).
tumor (continued). "In addition to the “do not eat me” signal, aberrant lipid accumulation in tumor-infiltrating DCs, caused by upregulation of the scavenger receptor Msr1 (CD204) and engagement of endoplasmic reticulum (ER) stress responses, robustly impedes the ability of DCs to prime T cells." (PMID 34290401, 2021). "On the other hand, common CNLs negatively influencing survival intervals harboured important tumour suppressors (e.g. CSMD1, MTUS1, MSR1, DBC2, and TUSC3) and genes enriching biological processes that would normally prevent cellular movement." (PMID 31969654, 2020). "In the multivariate analysis, copy-number losses (CNLs) in chromosome B1 (1–23 Mb) harbouring several tumour-repressors (e.g. CSMD1, MTUS1, MSR1, DBC2, and TUSC3) negatively influenced DFS." (PMID 31969654, 2020). "In line with our in vitro data, tumor samples displayed higher expression of the proliferation marker MKI67 and also contained more MΦ marker MSR1." (PMID 30615637, 2019). "Increased expression of KLRC1, CCL5, PLP1, CD163, MSR1, and GPNMB was found following treatment and tumor recurrence." (PMID 30151353, 2018). "ONECUT1, ADAMTS, IFNAR2, MSR1, and SORL1 affect migration or metastasis, a process that involves attachment of tumor cells to the basement membrane, degradation of local connective tissue, and penetration and migration of tumor cells through stroma." (PMID 23151184, 2012). "Finally, in the available tumor types including PAAD, SKCM and BRCA, we evaluated the co-expression of MSR1 and co-stimulatory molecules for the same cell types in macrophages and DCs using single cell analysis." (PMID 38612803, 2024). "When evaluating cells related to the expression of MSR1, we observed that a negative correlation with tumor purity was observed, suggesting that the protein was mainly present in the tumor’s microenvironment." (PMID 38612803, 2024). "Four macrophage subclusters were annotated, including a CD14+MSR1+CD163-cluster (MA1) that were mainly found in samples collected from the primary tumor site (ovary) and thus not seen in our previous study." (PMID 38328306, 2023). "Also in these settings, the increased M2 phenotype triggered by the tumor cells was reverted upon SKI-II treatment, as evident by reduced expression of Arg1 and Msr1 and enhanced expression of Tnfα and Il-6." (PMID 36672428, 2023). "The lack of MSR1 significantly enhanced HSP- or LPS-mediated vaccine activity against poorly immunogenic tumours." (PMID 36325338, 2022). "Furthermore, infiltration of MSR1-positive macrophages into the TME of colorectal cancer was connected to poor prognosis due to increased proliferation and invasion of tumour cells." (PMID 36325338, 2022). "On the other hand, CNLs in FCA B1 1–23 Mb (human homologue region located in HSA 8p) were significant in multivariate analysis and harboured multiple tumour suppressors (e.g. CSMD1, MSR1, MTUS1, and TUSC3) previously correlated with poor prognosis in HBCs15,19,23,27,70." (PMID 31969654, 2020). "Furthermore, our qPCR results also showed that the transcription level of MSR1 in THCA tumor tissues was significantly increased compared to adjacent normal tissues." (PMID 39502334, 2024). "Moreover, our bioinformatic analyses in individuals with cancer demonstrate that CDA levels are highest in 11 different tumor types with immunosuppressive features (that is, high in P2RY6, MRC1 and MSR1 levels in macrophages and low in IFNG and PRF levels in CD8+ T cells)." (PMID 38844817, 2024). "Lastly, to further understand the role of MSR1 in tumor immune responses, we utilized seven algorithms including TIMER, EPIC, IPS, MCP-counter, xCELL, CIBERSORT, and QUANTISEQ to assess the relationship between MSR1 expression and the infiltration of immune cells at different levels." (PMID 39502334, 2024). "Therefore, the correlation between MSR1 expression in tumour cells and carcinogenesis has not been well studied so far." (PMID 36325338, 2022).
tumor (continued). "The large monocyte/macrophage tumour infiltrate is also altered by CHK1i+LDHU treatment, with downregulated expression of CD206 and CD163, markers of classically activated M2 macrophages, and increased expression of iNOS and Msr1, markers of alternatively activated M1 macrophages." (PMID 34359633, 2021). "Furthermore, multiple receptors interacting with different S100 proteins or S100A8/A9 heterodimers are expressed by both tumor cells and TAMs (SCARA/B, CD36), preferentially by TAMs (AGER, MSR1, TLR4) or by tumor cells (ERBB2), pointing to extensive functional interactions between both cell types." (PMID 27215396, 2016). "This resulted in the down-regulation of Msr1 and at least a four-fold decrease in BODIPY staining on the tumor-derived DCs that were incubated with anti-Msr1 compared to those tumor-derived DCs that did not receive the Msr1 antibody (MFI 2669 and 630, respectively)." (PMID 22911764, 2012). "However, the immunogenicity seen with the inhibition of Msr1 on tumor derived DCs is not through the induction of IL-1β, as we show that irradiated tumor derived DCs produce significantly more IL-1β than non-irradiated tumor derived DCs incubated with either no, 10,25 or 50 ug/ml of Msr1." (PMID 22911764, 2012). "The TME is a complex ecosystem regulated by multiple interacting pro-tumor and anti-tumor signals, and we have not yet fully elucidated all the specific mechanisms by which CPVL and MSR1 function in TAMs." (PMID 39776914, 2024). "Within this region, there are established tumor suppressors (DLC1, DOK2 and LZTS1), as well as potential tumor suppressor genes (CSMD1, MTUS1, and MSR1), and many other genes not established in cancers." (PMID 35994499, 2022). "Thirdly, TNM staging was lost in a large number of samples, so we failed to combine TIIC in OS, MSR1, and TLR7 with tumor stage and grade, which required further verification." (PMID 33381518, 2020).